INS (insulin)
Diseases named in the same sentence as INS in open-access papers (continued):
Sharing a sentence is not in itself a finding about the gene and the disease.
Insulin resistance (continued). "When PRL concentrations are low within the physiologic range, adiponectin production is down-regulated, which causes an inflammatory state that might increase insulin resistance and decrease insulin sensitivity." (PMID 36471299, 2022). "Thus, we conclude that TNF-α disrupts the regulation of leptin on the β cell GSIS function by inhibiting leptin receptor LepRb and thus producing excessive insulin secretion related to hyperinsulinemia, which is postulated to be a cause of insulin resistance." (PMID 35198097, 2022). "The progressive loss of the skeletal muscle might lead to diminished insulin-mediated glucose disposal and exacerbated insulin resistance, resulting in severe glucose abnormalities." (PMID 35909561, 2022). "Interestingly, CIDEC KO mice exhibit higher mitochondrial oxidation and insulin sensitivity, but adipose tissue-specific knockdown causes hepatosteatosis and insulin resistance in HFD-fed mice." (PMID 35963433, 2022). "Insulin resistance (IR) is linked with Alzheimer’s disease (AD), and dysregulation in the molecular mechanism of insulin secretion may lead to histopathological lesions in AD." (PMID 36497027, 2022). "Increased expression of PTEN negatively impacts insulin sensitivity and may cause insulin resistance in insulin-dependent cells." (PMID 36497428, 2022). "However, in some cases, an increase in serum insulin levels is observed in late pregnancy, often associated with insulin resistance, which can lead to glucose hypersensitivity and type 2 diabetes—gestational diabetes mellitus (GDM)." (PMID 36013366, 2022). "An increase in the plasma concentration of free fatty acids (FFA) is a quite often complication of visceral fat depot and overexposure of hepatic and extrahepatic tissues to FFA can cause disturbances in insulin metabolism which is resulted with insulin resistance and DM." (PMID 36326381, 2022). "Finally, a Japanese study has found that a single nucleotide polymorphism of apoJ (rs22795590) is associated with a higher risk of T2D through both an increase in insulin resistance and an impairment of insulin secretion." (PMID 35130909, 2022). "The levels of F-K1057 and F-K1079 in WBCs of patients with T2D were not only higher than those of the non-T2D subjects but also positively correlated with HbA1c levels, consistent with F-K1057 and F-K1079 levels underlying insulin signaling inhibition and insulin resistance." (PMID 35879296, 2022). "Insulin resistance can be associated with multiple etiologic factors and refers to a complex pathological condition in which insulin-dependent cells have an inappropriate cellular response to insulin." (PMID 35327570, 2022). "HFFD consumption was implicated in the development of MS, which was linked with dyslipidemia, insulin resistance, hepatic oxidative stress, inflammatory condition, and alteration in hepatic expression of genes involved in lipid metabolism and insulin signaling transduction." (PMID 35990819, 2022). "Following the demonstration that elevated circulating insulin causes renal sodium retention, it was suggested that hyperinsulinemia resulting from insulin resistance might have a role in the mechanisms of salt sensitivity in hypertension." (PMID 36289636, 2022). "Defects in the expression of critical elements of insulin signalling are known to cause insulin resistance in mammalian skeletal muscle, and these impairments in insulin action are associated with the development of prediabetes and type II diabetes mellitus (T2DM)." (PMID 36112580, 2022). "Insulin-stimulated glucose uptake in skeletal muscle is of fundamental importance to prevent postprandial hyperglycemia, and long-term deficits in insulin-stimulated glucose uptake underlie insulin resistance and type 2 diabetes." (PMID 35774142, 2022). "Second, NAFLD can cause insulin resistance and augment the amount of circulating insulin." (PMID 36438843, 2022).
Insulin resistance (continued). "It changes the action of insulin on hepatic gluconeogenesis and causes insulin resistance in the hypothalamus that may conduct the development of peripheral insulin resistance." (PMID 36210435, 2022). "However, excessive obesity, especially high visceral fat content, is associated with insulin resistance and elevated insulin levels in the circulation." (PMID 36684119, 2022). "Indeed, ZnT7-KO mice show diet-induced glucose intolerance and insulin resistance, and it is known that ZnT7 deficiency inhibits insulin-dependent Akt activation and glucose uptake." (PMID 36233134, 2022). "Since insulin resistance and bone metabolism share a similar pathophysiology, abnormal signaling of insulin could cause dysregulation of osteoblast activity and osteoclast differentiation, leading to bone damage and osteoporosis." (PMID 36093833, 2022). "Moreover, in individuals with impaired glucose tolerance, plasma levels of 2-HB associate with hyperglycemia and insulin sensitivity and are an early marker for insulin resistance and risk for future T2D." (PMID 35931683, 2022). "Because insulin is recognized for its growth capabilities, it’s possible that a state of excess insulin, such as hyperinsulinemia caused by insulin resistance, could result in the birthing of diverse masses throughout the body." (PMID 35457158, 2022). "Insulin sensitizers are used to treat insulin resistance associated with PCOS." (PMID 36117653, 2022). "Insulin resistance is caused primarily by abnormalities in insulin signal transduction." (PMID 36589630, 2022). "Prior studies have demonstrated a close association between brain insulin resistance and Alzheimer’s disease (AD), while selenium supplementation was shown to improve insulin homeostasis in AD patients and to exert neuroprotective effects in a mouse model of AD." (PMID 35875664, 2022). "There is a paucity of evidence whether a higher post-load insulin response induced by insulin resistance is a risk factor for CVD mortality in people with normal glucose status and IGT." (PMID 35090539, 2022). "Thus, it is likely that the copresence of low serum levels of choline and CDKAL1 rs7747752 genetic variant led to a markedly increased risk of GDM via increasing insulin resistance or decreasing insulin sensitivity." (PMID 36183068, 2022). "Branched-chain amino acids (BCAA) another component of red meat, have also been positively associated with insulin resistance and T2D, with studies indicating elevated plasma concentration of BCAAs may impair insulin signaling activity." (PMID 36235806, 2022). "Excess nutrients and particularly BCAAs may cause insulin resistance due to the activation of the mTORC1, the well-known regulator of skeletal muscle insulin signaling and metabolism." (PMID 35409380, 2022). "The lower basal SAT ZAG expression percentile was associated with higher weight and waist circumference, while the lower basal VAT ZAG expression percentile was associated with higher weight, waist circumference, insulin, insulin resistance, and the presence of metabolic syndrome." (PMID 35884810, 2022). "Given that insulin signaling is a major regulator of systemic metabolism and insulin resistance is a hallmark of obesity, we asked whether HSD-fed flies display dysfunctional insulin signaling." (PMID 36201241, 2022). "However, one study revealed that in mice with vitamin B6 deficiency, insulin levels remained intact, though insulin resistance increased." (PMID 36501046, 2022). "Increasing evidence shows that sustained oxidative stress may cause T2D, which involves impaired insulin secretion and insulin resistance." (PMID 36217412, 2022). "Furthermore, elevated insulin levels, insulin-like growth factor binding protein-1, and greater insulin resistance were associated with Anti-β2GP1 levels." (PMID 36050731, 2022).
Insulin resistance (continued). "Similarly, exercise increases adiponectin concentration, which improves cellular sensitivity to insulin, and reduces inflammatory markers associated with insulin resistance." (PMID 36360995, 2022). "This early lipolysis, resulting from dysregulated hypothalamic control, causes hepatic insulin resistance (portal hypothesis) and blunts insulin signaling by activating PKC pathways, among other mechanisms." (PMID 36009446, 2022). "Microvascular dysfunction impairs glucose and insulin intake at a cellular level and may cause insulin resistance." (PMID 35784974, 2022). "Second, air pollution might disrupt insulin signaling and cause insulin resistance via inducing the production of endogenous pro-inflammatory mediators and vasoactive molecules." (PMID 36429390, 2022). "It has been stated that the increased level of insulin, which is common in type 2 DM due to insulin resistance, causes leptin overproduction, which in turn, increases leptin concentration, is related to the risk of incidence and progression of endometrial and ovarian cancers." (PMID 34751020, 2022). "Subsequent increases in insulin levels may then cause a compensatory increase in insulin resistance in peripheral tissues." (PMID 34302684, 2022). "Because phenotypes A and B were considered as classic PCOS and can possess more menstrual dysfunction, higher androgen and insulin levels, increased rate of insulin resistance and being at higher risk of metabolic syndrome and obesity comparing to non HA-phenotypes." (PMID 36155624, 2022). "Disruption of insulin and circadian regulation of lipolysis and food intake is associated with obesity, insulin resistance, and metabolic diseases." (PMID 36246998, 2022). "In contrast, insulin resistance may contribute to skeletal muscle loss because insulin promotes protein synthesis as well as glucose uptake." (PMID 35809101, 2022). "Finally, the associations of RGS8, RGS13, RGS18, and RGS21 with insulin secretion or insulin resistance need to be further investigated." (PMID 36497154, 2022). "A vast number of studies has provided evidence indicating that activation of peripheral CB1R located in insulin-dependent tissues, i.e., liver, adipose tissue, or skeletal muscles, is widely associated with the development of dyslipidemia, insulin resistance, and type 2 diabetes." (PMID 35328503, 2022). "Fetal insulin resistance, fetal growth, and therefore, the risk of macrosomia might be positively associated with insulin and C-peptide concentration in UC blood." (PMID 36224521, 2022). "Skeletal muscle is the most prominent site of insulin-mediated glucose uptake in humans, and enhancers in skeletal muscle have been reported to overlap association signals for metabolic disorders, including T2D, insulin resistance and obesity." (PMID 35220425, 2022). "Hence, insulin resistance, hyperinsulinemia, and impaired insulin signaling have been determined to cause many cognitive pathologies." (PMID 36232867, 2022). "Finally, we assessed if a classification of risk phenotypes according to insulin secretion and/or insulin-resistant fatty liver disease indicated different changes in 2 h glucose levels, when comparing the phenotypes." (PMID 36432409, 2022). "Furthermore, reduced activity of insulin-dependent enzymes in neutrophil granulocytes, causing impaired neutrophil migration, is also affected by relative insulin deficiency associated with insulin resistance in type 2 DM, or its complete absence in type 1 DM." (PMID 35887276, 2022). "In our present study, SerpinB1 was positively associated with insulin sensitivity index and better blood glucose level, and negatively correlated with hyperlipidemia and hyper-concentration of γGTP, which were related to hepatic insulin resistance." (PMID 36331940, 2022).
Insulin resistance (continued). "The pathogenesis of type 2 diabetes involves two primary metabolic defects: impaired insulin secretion and insulin resistance, defined as a reduction of tissue insulin sensitivity caused by a loss/downregulation of the insulin receptors (IR) or insulin receptor substrates (IRS-1 and IRS-2)." (PMID 35391928, 2022). "Increased insulin resistance and impaired insulin secretion are the main causes of GDM." (PMID 35606885, 2022). "Furthermore, our recent study documented a strong association between insulin resistance, elevated insulin levels and senescence in the livers of NAFLD/NASH patients (our unpublished data)." (PMID 35872305, 2022). "Insulin resistance, which remains a major metabolic abnormality in the great majority of patients with Type 2 diabetes, is caused by altered functions within the insulin target cells and the accumulation of macrophages secreting proinflammatory mediators, such as IL-6, TNFα, IL-8, and MCP-1." (PMID 36015180, 2022). "Moreover, the long-term use of insulin increases insulin receptor sensitivity and causes insulin resistance." (PMID 36422117, 2022). "Type 2 diabetes, obesity, and metabolic syndrome (hereafter referred to as “diabesity”) associated with increased insulin resistance and/or decreased insulin sensitivity have also been implicated with mitochondrial dysfunction and alterations in energy metabolism." (PMID 36531176, 2022). "Taken together, these findings suggest reduced SWELL1 activity in adipocytes and β-cells (and possibly other tissues) may underlie insulin resistance and impaired insulin secretion associated with T2D." (PMID 35145074, 2022). "Although insulin resistance is a common underlying mechanism of metabolic syndrome, a few studies have demonstrated a direct relationship between lifestyles and insulin resistance, especially in Asians with lower insulin secretion capacity." (PMID 35054379, 2022). "Dysregulated miRNA levels during gestation could contribute to decreased insulin sensitivity, an inappropriate response to the increasing insulin resistance associated with pregnancy and, ultimately, to impaired glucose metabolism." (PMID 35203692, 2022). "Impaired insulin-glucose homeostasis may contribute to loss of muscle mass, while loss of muscle mass may result in worsening dysglycemia, insulin resistance, and T2D." (PMID 36490255, 2022). "Third, lower levels of 25(OH)D concentrations are associated with insulin resistance, and vitamin D supplementation may improve insulin production and insulin sensitivity." (PMID 35360696, 2022). "Diabetic patients are severely deficient in insulin secretion due to the massive destruction of beta-cell mass (BCM), causing type 1 diabetes, or deficient in insulin response due to insulin resistance at early phase and decrease in BCM eventually, causing type 2 diabetes." (PMID 35408679, 2022). "New evidence shows that FAT10 plays a role in mitophagy, autophagy, insulin signaling, insulin resistance, and inflammation which may be directly associated with fatty liver disease development." (PMID 36386217, 2022). "The role of insulin sensivity and insulin resistance in the association between mood, stress, and disease pathogenesis is a promsing area for future research, with compelling theoretical arguments and burgeoning empirical evidence for the links, as described by Rasgon and McEwen." (PMID 34357581, 2022). "Clusterin can bind insulin, and its deficiency exacerbates insulin resistance in T2D77." (PMID 35383192, 2022). "Furthermore, reduced Akt is associated with skeletal muscle insulin resistance, in line with our previous observation that Ism1-KO mice fed a high-fat diet are more insulin resistant." (PMID 36169399, 2022). "As gestation progresses, sensitivity to insulin attenuates, causing a state of insulin resistance." (PMID 35745174, 2022).
Insulin resistance (continued). "As the loss of muscle mass and development of insulin resistance (i.e. impaired insulin‐stimulated glucose uptake) negatively affect our healthspan, there is ongoing focus on designing effective interventional strategies to preserve muscle mass and metabolic health in catabolic situations." (PMID 35415892, 2022). "The present analysis was based on the hypothesis that insulin sensitivity (IS)/insulin resistance (IR) may mediate the association of vitamin D status (25OHD) on resting energy expenditure (REE)." (PMID 35365764, 2022). "Visceral fat has a detrimental impact on insulin sensitivity as adipose tissue is linked with unfavourable secretion of hormones and pro-inflammatory chemicals, glycerol, leptin, cytokines, and lower secretion of adiponectin exacerbating insulin resistance." (PMID 36297122, 2022). "In summary, MppBMI has been consistently associated with both higher levels of insulin and insulin resistance in child offspring, supporting a potential underlying causal relationship, and this association is only partially explained (and therefore mediated) by the offspring BMI." (PMID 35669689, 2022). "Furthermore, insulin resistance refers to the decrease even loss of sensitivity of target tissues to insulin, leading a certain amount of insulin cannot achieve the expected biological effects." (PMID 35153796, 2022). "It is generally accepted that obesity and body fat distribution are closely associated with insulin resistance, and that this association may explain, at least in part, the heterogeneity observed in insulin sensitivity in healthy human populations." (PMID 36028540, 2022). "Thus, the aim of our study was to analyze the association between fasting insulin equivalents for adiposity variables (obesity, overweight, and elevated waist circumference) and insulin resistance markers in Brazilian adolescents." (PMID 36079745, 2022). "Reduced brain glucose uptake associated with impaired glucose tolerance and insulin resistance has also been observed in mice with brain-specific knockout of the insulin-dependent GLUT4 transporter, suggesting a role for the transporter in the homeostatic regulation of glucose." (PMID 35052794, 2022). "The insulin resistance that is associated with cancer cachexia is another possible mechanism that could account for fat loss, as insulin signaling suppresses lipolysis through mTORC1." (PMID 35319749, 2022). "In addition, some studies point to insulin resistance at the level of the pancreatic β cells as an important determinant of impaired insulin secretion, the best predictor of future loss of glucose homeostasis." (PMID 35055114, 2022). "For example, insulin levels follow a regular circadian rhythm in humans, peaking during the day and dropping at night and disruption of molecular circadian rhythms causes insulin resistance and elevated blood glucose." (PMID 36042214, 2022). "Metformin causes increased insulin sensitivity and highlights the role of insulin resistance in HS." (PMID 36499573, 2022). "In the state of insulin resistance, the impairment of insulin signaling in mesangial cells (MCs) might cause hypertrophy, proliferation, and matrix deposition of MCs." (PMID 35645822, 2022). "Rare heterozygous mutations in TBC1D4, which regulates insulin-responsive glucose transport, also may cause severe insulin resistance." (PMID 35618782, 2022). "Second, we could not investigate the association of these indices with hemoglobin A1c, fasting insulin, and insulin resistance." (PMID 35959273, 2022). "More recent studies have yielded additional support for our finding; DII is reported to be directly related to all markers of T2D risk, including fasting insulin, fasting glucose HbA1c, homeostasis model assessment index for insulin resistance (HOMA2-IR), and two-hour glucose levels." (PMID 35685508, 2022).